WFDC10A (WAP four-disulfide core domain 10A)
Synonyms: C20orf146; WAP10; dJ688G8.3
Tractability: Antibody: UniProt places it where antibodies can reach, with high confidence; UniProt predicts a signal peptide or a membrane-spanning region; its Gene Ontology location is reachable by antibodies, with medium confidence.
Gene: Protein-coding gene on chromosome 20 (45,629,739 to 45,631,196, forward strand). Ensembl gene ENSG00000180305.
Subcellular location: Secreted
Gene Ontology:
Molecular function: serine-type endopeptidase inhibitor activity; peptidase inhibitor activity
Biological process: antibacterial humoral response; innate immune response
Cellular component: extracellular region
Genetic constraint (gnomAD): Loss-of-function variants: 3 observed, 2.78 expected, observed/expected ratio (o/e) 1.08, 90% interval 0.46 to 1.88. That is too few expected variants to judge how well the gene tolerates losing a copy. Missense variants: 84 observed, 93.08 expected, observed/expected ratio (o/e) 0.9, 90% interval 0.76 to 1.08. Synonymous variants: 36 observed, 34.83 expected, observed/expected ratio (o/e) 1.03, 90% interval 0.79 to 1.37.
Homologues: Orthologues: chimpanzee WFDC10A (100% identical), macaque WFDC10A (91% identical), pig WFDC10A (65% identical), dog WFDC10A (63% identical), rabbit WFDC10A (58% identical), rat Wfdc10a (52% identical), mouse Wfdc10 (49% identical), Drosophila melanogaster CG5639 (23% identical), Caenorhabditis elegans C08G9.2 (15% identical). Paralogues in human: WFDC10B (65% identical), WFDC9 (34% identical), WFDC13 (32% identical), WFDC11 (27% identical), WFDC3 (27% identical), WFDC5 (25% identical), PI3 (20% identical), SLPI (19% identical), WFDC12 (19% identical).
Diseases named in the same sentence as WFDC10A in open-access papers:
WFDC10A is named in the same sentence as 2 diseases in open-access papers, as found by Europe PMC text mining. Sharing a sentence is not in itself a finding about the gene and the disease.
WFDC10A shares sentences with these, for which no sentence is quoted: cancer (1 paper); tumor (1).